MICA (MHC class I polypeptide-related sequence A)
Diseases named in the same sentence as MICA in open-access papers (continued):
Sharing a sentence is not in itself a finding about the gene and the disease.
tumor (continued). "Consistent with the previous study, our data demonstrate that 7C6 antibody is able to strongly inhibit the proteolytic shedding of MICA from MICA/B-bearing tumor cells, resulting in a substantial increase in the cell surface density of MICA." (PMID 32645836, 2020). "In this case, NK and CD8 cells cannot recognize tumor cells due to the low surface expression of MICA/B and the increased serum level of decoy MICA/B fragments." (PMID 32968163, 2020). "Overexpressed circ-0000977 serves as a sponge for miR-153 to counteract miR-153-mediated suppression of HIF-1α and ADAM10, promoting the shedding of membrane MICA (mMICA) from surface of tumor cells and converting into soluble MICA (sMICA)." (PMID 32587480, 2020). "Wan and his team reported that MICA is released into circulation due to shedding of MICA from cell membranes during tumor transformation or upon stress." (PMID 32010486, 2020). "Cytotoxic activity and recruitment of NK cells are also promoted by fever-range hyperthermia through upregulating MICA (MHC class I polypeptide-related sequence A) on tumor cells and its receptor NKG2D on NK cells." (PMID 32872532, 2020). "MICA was also expressed at significantly higher levels on metastatic as compared with primary tumours." (PMID 33207697, 2020). "Further, a valuable NKG2D feature is it sbinding to functionally redundant major histocompatibility complex (MHC) class I-like self-antigens (MICA) usually expressed at low levels in normal cells and overexpressed on tumor cells." (PMID 32668783, 2020). "Flow cytometric assessment of the tumor surface antigens MICA/B, and UL-16 binding proteins (ULBP) 2–6 on shN and shC cells revealed that shN typically have higher surface MICA/B levels, but lower levels of all ULBPs tested compared to shC cells." (PMID 32636849, 2020). "Entinostat, a narrow spectrum histone deacetylase inhibitor, increases MICA expression on tumor cells and NKG2D expression in primary NK cells even in hypoxic conditions, leading to enhancement of cytotoxicity of NK cells against tumor cells." (PMID 33287875, 2020). "Cancer-associated fibroblasts induce the shedding of the NKG2D ligands major histocompatibility complex (MHC) class I chain-related protein A and B (MICA/B) expressed on the tumor-cell surface by secreting high levels of metalloproteases (MMPs)." (PMID 33138017, 2020). "NKG2D is an essential NK activating receptor that can recognize tumor cells via binding to stress ligands (MICA, MICB, and ULBPs) expressed by transformed cells." (PMID 32784928, 2020). "The remaining 240 proteins were considered tumor-related differentially expressed proteins and included Vimentin, β-catenin, HLA-A/B/C, and MICA, among others." (PMID 33173143, 2020). "The proteolytic shedding of MICA and MICB by tumor cells causes immune escape via downregulation of these NKG2DL." (PMID 33424862, 2020). "The anti-tumor effect of Vγ9Vδ2 T cells depends on the phosphoantigens expressed by tumor cells but also on certain activator ligands (MICA/B and ULBPs) and adhesion molecules, essential to stabilize the immunological synapse." (PMID 32733462, 2020). "We recently discovered that tumor cell-associated NKG2DL, predominantly MICA and MICB, were cleaved following interaction with platelets or platelet releasate." (PMID 33424862, 2020). "In contrast, no anti-MICA antibodies were detectable in plasma of any of the B16F10-MICA tumor-bearing MICAgen mice testifying their immunotolerance for MICA." (PMID 32582150, 2020). "NKG2D is an important activating NKR which mainly recognizes stress-induced ULBP1-6 and MICA/B ligands on tumor or virally infected cells." (PMID 32153568, 2020). "In fact, all nontgLM bearing B16F10-MICA tumors raised a strong humoral anti-MICA response within 10–14 days post tumor inoculation, as their plasma contained high titers of MICA-specific antibodies up to 20 μg/ml." (PMID 32582150, 2020).
tumor (continued). "NK cells mainly identify tumor cells and initiate the killing process by recognizing MICA/MICB on tumor cells through the NKG2D receptor." (PMID 31980023, 2020). "Only poorly differentiated tumor tissue showed significantly increased MICA transcription compared to matched SNT tissue." (PMID 33266137, 2020). "NKG2D is bound to MHC class I-related chain A/B (MICB or MICA) on the tumor cell surface, which is upregulated in stem-like cancer cells preferentially." (PMID 33297519, 2020). "The activating receptor NKG2D induces NK cell-mediated killing of metastasizing tumor cells by recognition of the stress-induced ligands MICA, MICB, and ULBP1-6." (PMID 33424862, 2020). "Previous studies have shown that the major histocompatibility complex class I chain-related protein A (MICA) is shed from tumor cells via PDIA6 reducing the disulfide bond between them, facilitating the escape of tumor cells from immune responses." (PMID 32023222, 2020). "In studies of HCC, soluble MICA expression has been associated with poor prognosis; conversely, expression of ULBP1 on the tumor surface has been associated with improved survival." (PMID 32656081, 2020). "MICA shedding is considered as an immune escape mechanism of tumors evading NKG2D-mediated tumor immunosurveillance and has recently been successfully targeted in an immunotherapeutic approach using preclinical mouse models." (PMID 32582150, 2020). "Our in vitro and cell-based experiments suggest that soluble MICA mediates tumor immune escape through blocking of the NKG2D signaling pathway." (PMID 32010486, 2020). "The NKG2D ligands currently found on human tumor cells include MHC class I chain-related molecules (MICA, MICB) and six ULBP-binding proteins (ULBP1-6)." (PMID 32413966, 2020). "The expression of the NKG2D ligand MICA/B is dysregulated in various tumor cells, including HCC, which express MICA/B, their level of expression being correlated with the outcome of the disease." (PMID 33266137, 2020). "Here we show that MICA-antibody is a specific agent, capable of stabilizing the MICA/B expression on tumor cells and promoting the antitumor activity of CIK cells." (PMID 32645836, 2020). "To understand if the decrease in serum sMICA/B concentrations in patients with G3 HCC was due to a reduction in gene transcription, we measured MICA mRNA levels in G2 and G3 tumor tissue and in their matched surrounding non-tumor (SNT) specimens." (PMID 33266137, 2020). "As an important component of NKG2DLs, MICA/B expression is restricted to tumor tissues and plays key roles in mediating the cytotoxicity of NK cells." (PMID 31088566, 2019). "MICA is highly expressed in tumor cell lines and epithelial-derived primary tumors, such as lung, breast, liver, and prostate cancers." (PMID 31419949, 2019). "Gefitinib can upregulate the expression of ULBP1, ULBP2, and MICA in tumor cells and can promote the expression of NKG2D in NK cells, thereby inhibiting tumor escape." (PMID 30813924, 2019). "It has also been shown that HIF-1 is able to downregulate MICA expression in osteosarcoma cells, resulting in tumor resistance to NK-mediated lysis." (PMID 31396523, 2019). "Modulation of cell surface expression of MHC class I chain-related protein A/B (MICA/B) has been proven to be one of the mechanisms by which tumor cells escape from NK cell-mediated killing." (PMID 31088566, 2019). "In parallel, immunohistochemistry (IHC) analyses showed strong expression of NKG2D ligand MICA/B on tumor cells in both control and cocultured spheroids." (PMID 30871626, 2019). "Compared to its control isotype, anti-MICA/B induced an increased immune-dependent spheroid destruction and tumor cell death, as observed by microscopic data, live-imaging and flow cytometry (respectively)." (PMID 30871626, 2019). "It is also worth noting that our results were obtained using a tumor cell line that ectopically expresses MICA." (PMID 31387641, 2019).
tumor (continued). "The reactive oxygen species (ROS)-induced DNA damage response promotes tumor immunity by binding the transcription factor E2F1 to the E2F1 binding site adjacent to the transcription initiation site of the MICA promoter." (PMID 30813924, 2019). "In some tumour models, forced expression of the membrane-bound NKG2DLs, MICA and murine Rae-1ε, were reported to impair NKG2D function through chronic receptor stimulation." (PMID 30626155, 2019). "Altogether, we show that tumor spheroids represent a relevant tool to study tumor-lymphocyte interactions on human tissues and revealed the antitumor potential of immunomodulatory antibodies targeting MICA/B and NKG2A." (PMID 30871626, 2019). "Blocking the α3 domain using domain-specific antibodies has shown to stabilize the MICA/B on tumor cells to strongly prevent shedding and stimulate tumor immunity." (PMID 31396523, 2019). "Compared to non-tumor tissues (N), a variety of factors like TGF-β1, TGF-β2, HMGB1, PVR, nectin-2, galectin-9, PD-L1, PD-L2, and MICA/MICB were significantly higher in the tumor tissue (T)." (PMID 31234517, 2019). "Spheroid infiltration by immune cells as well as spheroid destruction and tumor cell apoptosis were significantly decreased in this condition (respectively), suggesting that MICA/B are major targets of cytotoxic cells infiltrating spheroids." (PMID 30871626, 2019). "In this experiment, we elucidate a new phenomenon that MICA/B can be down-regulated by tumor microenvironment such as high glucose." (PMID 31088566, 2019). "It was previously thought that shed MICA/B dampens NKG2D-dependent anti-tumor immunity by masking cell surface NKG2D receptor and inducing NKG2D down-regulation." (PMID 31387641, 2019). "Anti-MICA/B enhanced immune-dependent destruction of tumor spheroid by driving an increased NK cells infiltration and activation." (PMID 30871626, 2019). "Our results support these concepts, by showing that NKG2D blockade prevents immune infiltration and activation in tumor spheroids and that exploiting MICA/B as a tumor antigen to induce ADCC is a feasible and efficient approach." (PMID 30871626, 2019). "A recent study demonstrated that anti-MICA/B antibody enhanced NK cell-dependent destruction of tumor spheroids." (PMID 31387641, 2019). "Once activated by MICA via NKG2D, NK cells have the ability to kill self-cells deficient in MHC class I molecules, a property important to immunosurveillance as tumor cells are known to evade the adaptive immune system through MHC class I downregulation." (PMID 29090365, 2018). "We thus aimed to generate an ADC targeting MICA/B- expressing tumors with a dual function to achieve optimal therapeutic benefits: (i) killing of tumor cells and (ii) disrupting the interaction between MICA/B and NKG2D that induces impaired immunosurveillance." (PMID 30400835, 2018). "Current research also shows that hypoxia via tumor-derived microvesicles (TD-MVs) downregulates the expression of MICA (NKG2D ligand) on tumor cells, and the activating receptor NKG2D expression on human and murine NK cells." (PMID 29762526, 2018). "Tumor cells can escape from NKG2D mediated immune surveillance by proteolytic cleavage of membrane bound MICA molecules and formation of soluble forms in sera of HCC patients." (PMID 30214375, 2018). "MICA and MICB expression has been described in a variety of tumors and has been associated with an increased tumor infiltration by Vδ1+ T cells." (PMID 29707004, 2018). "Shedding of soluble MICA depends on its interaction with the chaperon molecule protein disulfide isomerase family A member six (PDIA6—best known as ERp5) on the surface of tumor cells." (PMID 30597841, 2018). "For example, hypoxia upregulates hypoxia inducible factor 1-alpha (HIF1α)-dependent ADAM10 expression resulting in MHC class I polypeptide-related sequence A (MICA) shedding from the surface and decreased lysis of tumor cells." (PMID 29963058, 2018).
tumor (continued). "As the biology of ULBP4 (RAET1E), ULBP5 (RAET1G), and ULBP6 (RAET1L) and their role in tumor immunity is poorly understood, we will focus on the well-studied five ligands MICA, MICB, ULBP1-3." (PMID 30254634, 2018). "MMP-2 has also been shown to be responsible for the shedding of the MHC class I polypeptide-related sequence A (MICA), which is important for stimulating natural killer (NK) and T-cell anti-tumor immunity." (PMID 29874869, 2018). "The antitumor responses of cytotoxic T lymphocytes like γδ T cells are mediated through recognition of stress molecules (ULBP, HSPs) or danger signals like MICA/B expressed on tumor cells by class of activating receptors known as NKG2D." (PMID 30072989, 2018). "Suppression of MICA and MICB decreases the susceptibility of tumor cells to the cytotoxicity of NK cells." (PMID 30046565, 2018). "Real-time quantitative PCR assays revealed a significant decreased mRNA expression of MICA MI genotype in tumour tissues compared to MA genotype (p = 0.048)." (PMID 28928439, 2017). "Among the NKG2DLs MICA/B and ULBP1/2/3, the expression levels of MICA/B in BC tissues were inversely associated with the Tumor Node Metastasis stage." (PMID 28383557, 2017). "The tumour secretes factors such as soluble MICA, MICB, and vesicles containing ULBP3, all of which impair NK cell cytotoxic ability, facilitating immune evasion." (PMID 28668076, 2017). "Since MICA antigens are also frequently found on tumor cells, it implies that they are cell stress markers and their tissular expression is a signal for destruction by NK cells." (PMID 28293239, 2017). "Studies have demonstrated that expression of MICA in tumor cells leads to the activation of NK cells via MICA/NKG2D interaction, which in turn release cytotoxic proteins and INF-γ." (PMID 28450866, 2017). "In accordance with previous observations, growth of B16F10 tumor cells ectopically expressing the human NKG2DL MICA*01 was accelerated in NKG2D-dysfunctional H2-Kb-MICA mice as compared to non-tgLM." (PMID 29163533, 2017). "Based on our results, it is likely that not only tumor cells can affect MICA/B membrane expression by the secretion of MMPs, but also stromal cells including CAFs." (PMID 28423623, 2017). "As a natural killer (NK) group 2D ligand, membrane-bound MICA triggers the immune system, thereby resulting in the elimination of target tumour cells via NK and CD8+T cells." (PMID 28928439, 2017). "Most studies on soluble MICA release in the serum have been directed toward understanding their influence on tumor growth, with very little literature available on the associated biology." (PMID 28293239, 2017). "Here we also found the MICA mRNA level were higher in liver tumour tissues compared to non-tumour area, down-regulated in MICA HE genotype, and lowest in MI genotype." (PMID 28928439, 2017). "We found that the protein expression of MICA/B was significantly higher in BC cells at early stages (Tumor Node Metastasis (TNM) stages I and II) than in BC cells at advanced stages (TNM stage III)." (PMID 28383557, 2017). "Another promising NK cell-focused bispecific platform is developed by AvidBiotics to target tumors that evade NK killing via downregulation or shedding of the NKG2D ligand MICA, which is a major limiting step in NK-mediated tumor targeting." (PMID 28620386, 2017). "Killing of MCF10A, MDA-MB-468 and HCC1143 cells by NK cells was indeed reduced after blockage of NKG2D on NK cells using an anti-NKG2D antibody or upon siRNA-mediated knockdown of MICA or ULBP2 in tumor cells." (PMID 28771222, 2017). "Similar to NK and CD8+ T cells, the γδ T cells express NKG2D which interacts with MICA/B on tumor cells and promotes secretion of perforin proteins and subsequent tumor lysis." (PMID 28116316, 2016). "To investigate the in vivo relevance of our in vitro results, we analyzed MICA expression in a tumor xenograft." (PMID 28154561, 2016).
tumor (continued). "The enhanced inhibition of Ki-67/VEGF/CD31 by mAb04-MICA were consistent with increased anti-tumor effects resulting from the presence of MICA." (PMID 26909862, 2016). "mAb04-MICA localized in tumor lesions via the recognition of mAb04 to tumor cell surface VEGFR2, and attracted NK cells to the tumor lesions through the associated MICA." (PMID 26909862, 2016). "It has been demonstrated in several reports that MICA or MICB proteins are shed by tumor cells in many types of cancers with potential prognostic value." (PMID 26909604, 2016). "The use of sections of the whole tumor also allowed us to determine the expression pattern of MICA and MICB." (PMID 26902929, 2016). "The expression of NKG2D ligands such as MICA and MICB render tumor cells more susceptible to being killed by NK and T cells." (PMID 26902929, 2016). "In contrast to classic MHC class I molecules, MICA/B are rarely expressed on normal cells but are frequently expressed on tumor cells." (PMID 27385218, 2016). "ADAM10 knockdown resulted in increased expression of membrane-bound MICA, decreased production of soluble MICA, and enhanced NK sensitivity of tumor cells." (PMID 27385218, 2016). "Previous studies have found that MICA shedding is considered a principal mechanism of tumor cells to escape from NKG2D-mediated immunosurveillance in humans." (PMID 27306684, 2016). "We have designed experiments to demonstrate mice have similar NK cells with human directly binding to MICA, which can help explain the anti-tumor effects of mAb04-MICA in the xenograft mouse tumor model." (PMID 26909862, 2016). "It has been shown that in some tumor cell lines delivery of control plasmid DNA caused significant increase in the expression of following ISGs: IRF7, STAT1, MIG, MICA and ITGAL." (PMID 26839680, 2016). "The role of FAK/Src in this process indicates a potential therapeutic approach to modulate MICA expression and immune recognition of tumor cells during metastasis." (PMID 28154561, 2016). "In T47D tumor cells which lack a MICA membrane expression, the MICB expression was found to be strongly reduced upon treatment with NZ28." (PMID 25854583, 2015). "Several studies confirmed the predominant relevance of NKG2D in efficient recognition and elimination of tumor- and “stressed” cells by targeted binding of MICA and MICB." (PMID 26579120, 2015). "Human NKG2D recognizes several structurally related ligands (NKG2DLs) on tumor cells from various cytological origin, including the MHC class I chain-related protein A (MICA), MICB, and the UL16-binding proteins (ULBPs)." (PMID 25933805, 2015). "Vice versa, a reduced MICA/B membrane expression on tumor cells impairs the recognition by NK cells and promotes tumor immune escape." (PMID 25854583, 2015). "An enhanced sensitivity of tumor cells to NK cell-mediated lysis has been attributed to an increased membrane expression density of the NKG2D ligands MICA and MICB." (PMID 25854583, 2015). "The MHC-unrestricted anti-tumor activity of CIK cells is mainly mediated by the interaction of NKG2D with MICA/B and ULBPs." (PMID 26418951, 2015). "The molecular mechanisms that regulate the expression of MICA/B on tumor cells are not completely understood." (PMID 25854583, 2015). "All tumor samples showed higher HER1 and CD9 levels in contrast to low-to-moderate expression of membrane-associated MICA and HER2 molecules." (PMID 26579120, 2015). "One tumor section expressed only one ligand (MICA); in the other seven biopsies, expression of at least a NKG2D and a DNAM-1 ligand was observed." (PMID 25854581, 2015). "TGF–β1 also interferes with several mechanisms of anti-tumor immune responses and selectively down-regulates MICA expression." (PMID 26008966, 2015). "In contrast, NZ28 completely blocked the MICA/B membrane expression on tumor cells and thereby strongly inhibited the NK cell-mediated cytotoxicity." (PMID 25854583, 2015).